HMX1 (H6 family homeobox 1)
Description:
DNA-binding protein that binds to the 5'-CAAG-3' core sequence. May function as a transcriptional repressor. Seems to act as a transcriptional antagonist of NKX2-5. May play an important role in the development of craniofacial structures such as the eye and ear.
Synonyms: H6; NKX5-3
Tractability: No criterion of Open Targets' tractability assessment is met for any kind of drug.
Gene: Protein-coding gene on chromosome 4 (8,846,076 to 8,871,839, reverse strand). Ensembl gene ENSG00000215612.
Subcellular location: Nucleus
Gene Ontology:
Molecular function: DNA binding; sequence-specific double-stranded DNA binding; DNA-binding transcription factor activity, RNA polymerase II-specific; RNA polymerase II transcription regulatory region sequence-specific DNA binding; DNA-binding transcription repressor activity, RNA polymerase II-specific
Biological process: negative regulation of DNA-templated transcription; regulation of transcription by RNA polymerase II; negative regulation of transcription by RNA polymerase II; regulation of DNA-templated transcription
Cellular component: chromatin; nucleus
Genetic constraint (gnomAD): Loss-of-function variants: 5 observed, 2.43 expected, observed/expected ratio (o/e) 2.06. That is too few expected variants to judge how well the gene tolerates losing a copy. Missense variants: 518 observed, 285.31 expected, observed/expected ratio (o/e) 1.82, 90% interval 1.69 to 1.94. Synonymous variants: 263 observed, 140.96 expected, observed/expected ratio (o/e) 1.87, 90% interval 1.68 to 1.98.
Gene-disease validity (ClinGen):
ClinGen rates the evidence that HMX1 causes each of these diseases.
oculoauricular syndrome (autosomal recessive): Definitive.
Homologues: Orthologues: chimpanzee HMX1 (99% identical), macaque HMX1 (99% identical), dog HMX1 (94% identical), pig HMX1 (93% identical), rat Hmx1 (87% identical), mouse Hmx1 (86% identical), guinea pig HMX1 (73% identical), tropical clawed frog hmx1 (40% identical), zebrafish hmx1 (34% identical), Caenorhabditis elegans mls-2 (24% identical). Paralogues in human: HMX3 (39% identical), HMX2 (27% identical), HOXA9 (15% identical).
Diseases named in the same sentence as HMX1 in open-access papers:
HMX1 is named in the same sentence as 26 diseases in open-access papers, as found by Europe PMC text mining. Sharing a sentence is not in itself a finding about the gene and the disease. The quoted sentences say what the papers report.
oculoauricular syndrome (5 papers, 2013 to 2023). "A homozygous missense mutation (c.650A>C; p.(Gln217Pro)) that abrogates the HMX1 function results in a rare oculoauricular syndrome associated with congenital cataracts, anterior segment dysgenesis, and retinal dystrophy." (PMID 36009466, 2022). "In human, recessive loss of function mutations in HMX1 have been associated with oculoauricular syndrome (OAS, OMIM 142992) characterized by malformation of the external ear and eyes." (PMID 32552830, 2020). "Meanwhile, homozygous mutation in the human HMX1 gene leads to abrogation of gene function causing oculoauricular syndrome (OAS, OMIM #612109) affecting both the eye and external ear." (PMID 32552830, 2020). "More recently, the discovery of an HMX1 loss-of-function mutation responsible for a new oculoauricular syndrome (MIM 612109) in a Swiss consanguineous family prompted us to evaluate the role of this transcription factor." (PMID 23946633, 2013). "This would help in understanding the bases of the human oculoauricular syndrome caused by Hmx1 mutation." (PMID 23946633, 2013). "Mutations in HMX1 (human NKX5-3) alleles cause ear deformities in multiple species, including the “misplaced ears” phenotype in mice, the dumbo (dmbo) phenotype of “fancy” rats, and oculoauricular syndrome in humans." (PMID 37255601, 2023). "Genes down-regulated in rx3-/- mutants are mostly associated with eye diseases, including microphthalmia (rx2, rx3, vsx2, six6b and aldh1a3) and oculoauricular syndrome (hmx1)." (PMID 25266257, 2014).
microphthalmia (4 papers, 2009 to 2021). Congenital or developmental anomaly in which the eyeballs are abnormally small. "A single C > T mutation that changes Glu65 to an amber stop codon in the Hmx1 gene displays microphthalmia, protruding ear and craniofacial malformations in mice." (PMID 32111086, 2020). "Hmx1 is highly expressed in the developing eye, and humans with mutations in the orthologous HMX1 (NKX5-3) gene exhibit a variety of ophthalmic anomalies including microphthalmia, anterior segment dysgenesis, cataracts and colobomata." (PMID 19379485, 2009). "Delayed withdrawal of retinal progenitors from the cell cycle resulting in retarded retinal differentiation and microphthalmia were observed after morpholino-mediated knockdown of Hmx1 in zebrafish." (PMID 32111086, 2020).
microtia (4 papers, 2014 to 2023). "A duplication mutation in ECR near HMX1 modified by a SNP in GATA6 exon seven plays a significant role in Awassi sheep microtia." (PMID 32481741, 2020). "Results showed mutations in only two genes significantly associated with microtia in Awassi: duplication in part of ECR near HMX1 (6:114293121-6:114293196) and a SNP at GATA6 exon 7 (23:34498242)." (PMID 32481741, 2020). "The EVC gene was selected for its roles in cartilage development, and the NKX3-2 and HMX1 gene was for their link to syndromic microtia." (PMID 24983964, 2014). "Although their results suggested a perfect association between the duplication mutation in ECR near HMX1 and microtia, our results found two microtia samples without this mutation." (PMID 32481741, 2020). "The HMX1-ECR duplications were specifically associated with isolated bilateral concha-type microtia but not with other ear malformations or syndromic microtia." (PMID 32552830, 2020). "Thus, isolated microtia and syndromic microtia without eye affects are unlikely to be caused by mutations in the HMX1 coding region." (PMID 32552830, 2020). "Based on the knowledge that microtia is one of the facial deformities with cartilage abnormity, we suggest detailed investigations on the EVC, EVC2, SLC2A9, NKX3-2 and HMX1 genes for this isolated microtia pedigree." (PMID 24983964, 2014). "No CNVs were detected in HMX1-ECR regions in 61 patients with other type of microtia." (PMID 32552830, 2020).
Candidemia (2 papers, 2017 to 2023). A form of invasive candidiasis where species of CANDIDA are present in the blood. "miR-204/miR-211 mimics, targeting H6 Family Homeobox 1 (Hmx1), reduced kidney injury via immune suppression in candidemia-induced AKI mice." (PMID 37761260, 2023).
cataract (2 papers, 2009 to 2022). Partial or complete opacity of the crystalline lens of one or both eyes that decreases visual acuity and eventually results in blindness. "HMX1, GJA1, and PROSER3 were identified to be the leading genes associated with cataracts in our older population." (PMID 36009466, 2022).
congenital cataracts (2 papers, 2016 to 2022). "A previous genome-wide study of two individuals from a consanguineous family found an association of HMX1 with congenital cataracts." (PMID 36009466, 2022). "Although several transcription factors such as Pax6, PITX3, HSF4, and HMX1 were allelic with congenital cataracts, MAF family genes are well characterized for the indispensable transcription factor regulating lens development." (PMID 27631609, 2016).
neuroblastoma (2 papers, 2022 to 2026). Neuroblastoma (NB) is the most common solid, extracranial childhood tumor. "Amongst these genes were neuroblastoma-associated genes NTRK1, BCL11A, TH and CHGB, as well as HMX1, a transcription factor on chromosome 4 that is a master regulator of neural crest development." (PMID 36071103, 2022). "Similarly, a peptide expressed from HMX1 forms a highly stable complex with HLA-A2 and has widespread expression across neuroblastoma tumors, in agreement with a previous study by our group." (PMID 41477871, 2026).
candidiasis (1 paper, 2015). Infection with the organism Candida. "The HO (Hmx1) of the pathogenic yeast Candida albicans and its product, CO, also contribute to pathogenesis; mutagenesis of the HMX1 gene results in decreased virulence in murine candidiasis, whereas exposure of mice to therapeutic levels of CO increases C. albicans virulence." (PMID 26055702, 2015).
deafness (1 paper, 2020). An inherited or acquired condition characterized by the complete loss of the ability to hear from one or both ears. "Mutations or loss of NKL homeobox gene expression is associated with corresponding developmental defects: aberrations of HMX1 result in malformation of the outer ear and those of HMX2/3 in inner ear defects and deafness." (PMID 33048949, 2020).
ear malformation (1 paper, 2020). "We add to evidences in human that copy number variations in HMX1-ECR associates with ear malformations, as in other species." (PMID 32552830, 2020). "We add to evidence in humans that copy number variations in HMX1-ECR, a conserved non-coding elements (CNEs), associates with ear malformations, as in other species." (PMID 32552830, 2020). "We provide additional evidence that the dosage sensitive effects of HMX1 may result in different types of ear malformations." (PMID 32552830, 2020).
glioma (1 paper, 2021). A benign or malignant brain and spinal cord tumor that arises from glial cells (astrocytes, oligodendrocytes, ependymal cells). "We detected TF binding sites for E2F1, HMX1, PAX5, REST and ZBTB6 in the promoters of DEGs present within the top six ‘glioma TADs’." (PMID 34341417, 2021).
liver steatosis (1 paper, 2021). "As expected, the hMXs + Dox (hMX1 + Dox and hMX3 + Dox) groups at 24 dpf developed palpable liver steatosis, whereas control groups showed no or few fat accumulations." (PMID 34943942, 2021).
myelodysplastic syndrome (1 paper, 2021). A clonal hematopoietic disorder characterized by dysplasia and ineffective hematopoiesis in one or more of the hematopoietic cell lines. "However, HMX2 and HMX3 are aberrantly expressed in AML and the activity of HMX1 was detected in subsets of myelodysplastic syndrome (MDS) patients." (PMID 33921702, 2021).
retinal degeneration (1 paper, 2013). Degeneration of the retina. "A homozygous mutation in the H6 family homeobox 1 (HMX1) gene is responsible for a new oculoauricular defect leading to eye and auricular developmental abnormalities as well as early retinal degeneration (MIM 612109)." (PMID 23946633, 2013).
senile cataract (1 paper, 2022). A cataract with no obvious cause occurring in persons over 50 years old. "Although rs145208055, located near HMX1, was identified in our older population, the linkage between senile cataracts and HMX1 remains to be explored." (PMID 36009466, 2022).
spina bifida (1 paper, 2022). A congenital neural tube defect in which vertebrae are not fully formed. "Patients carrying mutations of HMX1 presented an additional subset of defective maxillomandibular structures and spina bifida." (PMID 35406651, 2022).
infection (4 papers, 2013 to 2026). The state of being infected such as from the introduction of a foreign agent such as serum, vaccine, antigenic substance or organism. "Of these, two were used in experimental mouse infection, and the deletion of the HMX1 gene was studied to assess its effect on virulence (DE35762; DE6507)." (PMID 41294354, 2026). "The MxA insensitivity of JOSV was further analyzed in vivo, using experimental infections of C57BL/6 mice that express the entire human MX1 gene locus as a transgene (hMX1-tg)." (PMID 33196685, 2020). "As expected, the hMX1-tg mice were completely resistant to rSiAr126(wt) even at a high infection dose of up to 100,000 pfu." (PMID 33196685, 2020). "Infection experiments with MxA-transgenic mice (hMX1-tg) revealed the antiviral potency of human MxA in vivo because these animals were fully protected against an otherwise lethal challenge with SiAr126." (PMID 33196685, 2020). "We observed that FTR1 pathway genes are expressed throughout the infection, but that the HMX1 pathway is induced in the latter stages of infection." (PMID 24146619, 2013). "It is conceivable that the HMX1 pathway induction observed in latter stages of the infection was a consequence of the haemoglobin accumulation in the kidney." (PMID 24146619, 2013). "However, in hMX1-tg mice only infection with rSiAr126-NP(R328V) yielded progeny viruses in liver, lung and spleen whereas rSiAr126(wt) was suppressed to undetectable levels in all tissues, indicating an efficient MxA escape of rSiAr126-NP(R328V) also in vivo." (PMID 33196685, 2020). "To exclude the possibility that JOSV failed to induce an IFN response in the hMX1-tg animals, we pretreated these animals with IFNαB/D before infection that was shown to induce MxA synthesis." (PMID 33196685, 2020). "Moreover, during infection in the presence of albumin, C. glabrata drastically changed the expression of genes involved in iron uptake (FTR1 and SIT1), intracellular iron distribution and consumption (FTH1, HMX1) and virulence (EPA1, YPS2, AUS1)." (PMID 34710198, 2021).
HMX1 also shares sentences with these, for which no sentence is quoted: atrial septal defect (1 paper); autosomal recessive retinitis pigmentosa (1); Doyne honeycomb retinal dystrophy (1); Leber congenital amaurosis (1); leiomyoma (1); Microcornea (1); Retinal dystrophy (1); Rod-cone dystrophy (1); Sepsis (1).